PCDHB1 (protocadherin beta 1)
Description:
Potential calcium-dependent cell-adhesion protein. May be involved in the establishment and maintenance of specific neuronal connections in the brain.
Synonyms: PCDH-BETA1
Tractability: Antibody: UniProt places it where antibodies can reach, with medium confidence; UniProt predicts a signal peptide or a membrane-spanning region; its Gene Ontology location is reachable by antibodies, with medium confidence.
Gene: Protein-coding gene on chromosome 5 (141,051,374 to 141,059,346, forward strand). Ensembl gene ENSG00000171815.
Subcellular location: Cell membrane
Subcellular location (Human Protein Atlas): Nucleoplasm; Plasma membrane
Gene Ontology:
Molecular function: cell adhesion molecule binding; calcium ion binding
Biological process: cell adhesion; homophilic cell-cell adhesion
Cellular component: plasma membrane; membrane
Genetic constraint (gnomAD): Loss-of-function variants: 44 observed, 45.95 expected, observed/expected ratio (o/e) 0.96, 90% interval 0.75 to 1.23. The upper end of that interval is the gene's LOEUF score, 1.23, which puts it in group 5 of 6, group 1 being the genes least tolerant of losing a copy. Missense variants: 919 observed, 1,071.1 expected, observed/expected ratio (o/e) 0.86, 90% interval 0.81 to 0.91. Synonymous variants: 392 observed, 428.56 expected, observed/expected ratio (o/e) 0.91, 90% interval 0.84 to 0.99.
Homologues: Orthologues: chimpanzee PCDHB1 (99% identical), macaque PCDHB1 (96% identical), rabbit PCDHB1 (88% identical), rat Pcdhb1 (88% identical), mouse Pcdhb1 (88% identical), dog PCDHB1 (87% identical), guinea pig PCDHB1 (87% identical), pig PCDHB1 (75% identical). Paralogues in human: PCDHB7 (51% identical), PCDHB15 (50% identical), PCDHB2 (50% identical), PCDHB5 (50% identical), PCDHB10 (49% identical), PCDHB3 (49% identical), PCDHB13 (49% identical), PCDHB14 (49% identical), PCDHB16 (49% identical), PCDHB9 (49% identical), PCDHB12 (49% identical), PCDHB6 (49% identical), and 49 more.
Diseases named in the same sentence as PCDHB1 in open-access papers:
PCDHB1 is named in the same sentence as 5 diseases in open-access papers, as found by Europe PMC text mining. Sharing a sentence is not in itself a finding about the gene and the disease. The quoted sentences say what the papers report.
cervical cancer (1 paper, 2013). A primary or metastatic malignant neoplasm involving the cervix. "Among the 49 PRC2 targets (defined by consistent hyper-MVPs) identified here were 10 genes of the cadherin superfamily in HPV+ HNSCC, including CDH8 and CDH13 (both also hypermethylated in cervical cancer, CDH18, CDH19, CDH23, PCDH10, PCDH15, PCDHB1, PCDHB4, and PCDHB15." (PMID 23419152, 2013).
neuroblastoma (1 paper, 2011). Neuroblastoma (NB) is the most common solid, extracranial childhood tumor.
Rett syndrome (1 paper, 2011). A severe neurodevelopmental disorder affecting the central nervous system. "Furthermore, PCDHB1 was up-regulated in postmortem brains from Rett syndrome patients." (PMID 21824415, 2011).
PCDHB1 also shares sentences with these, for which no sentence is quoted: oral cancer (1 paper); tumour (1).